TSHR (thyroid stimulating hormone receptor)
Diseases named in the same sentence as TSHR in open-access papers (continued):
Sharing a sentence is not in itself a finding about the gene and the disease.
hyperthyroidism (continued). "Because the patient had a history of hyperthyroidism, we considered whether the gene mutation was related to hyperthyroidism, so we conducted vitro tests to verify the expression and function of the mutant TSHR (mutTSHR) compared to the wide-type TSHR (wtTSHR)." (PMID 38241561, 2024). "There are relatively few reports in the literature on cases of hyperthyroidism with normal TSHR-Ab levels." (PMID 38813368, 2024). "At the primary examination conducted on 4 April 2022 — for in vitro fertilization procedure, the serum analysis unexpectedly revealed subclinical hyperthyroidism with normal TSHR-Ab." (PMID 38813368, 2024). "In TED, activation of the TSHR in orbital fibroblasts leads to an increased adipogenesis as well as an increased hyaluronan production In addition, hyperthyroidism is known to induce brown fat activity in BAT and BRITE fat." (PMID 37435490, 2023). "Hyperthyroidism is mainly due to the overactivation of the thyroid-stimulating hormone receptor (TSH-R) by stimulating antibodies (TSH-R-Ab)." (PMID 36834770, 2023). "In the late TSHR-immunized group, hyperthyroidism was found in 40% of individuals and a heterogeneous image was detected in 50% of the mice." (PMID 37435490, 2023). "5C9 inhibits the constitutive activity of TSHR and controls TSHR-related hyperthyroidism and thyroid cancer." (PMID 38111381, 2023). "Thyrotoxicosis is an autoimmune response characterized by the presence of autoantibodies targeting the TSH receptor (TSHR-Ab), resulting in goiter and hyperthyroidism." (PMID 38260150, 2023). "Characteristic changes of the morphology, indicative for hyperthyroidism were found in 80% of early TSHR-immunized mice but only in 22% of immunized mice after linsitinib treatment." (PMID 37435490, 2023). "GD is characterized by an abnormal number of autoreactive B cells that produce antibodies which bind to thyroid-stimulating hormone receptor (TSHR), overstimulating the thyroid and causing hyperthyroidism." (PMID 37047805, 2023). "For HT, apoptosis and subsequent fibrosis lead to the presence of hypothyroidism, while in GBD, the persistent stimulation of the TSHR by its autoantibody (TRAb) induces hyperthyroidism, goiter, and extrathyroidal manifestations." (PMID 36980259, 2023). "The etiology is primarily due to the presence of circulating anti-thyroid-stimulating-hormone receptor (TSH-R) stimulating autoantibodies in the body, which leads to hyperthyroidism." (PMID 37396175, 2023). "Conversely, GD is characterized by thyrocyte hyperplasia (goiter) and excess thyroid hormone synthesis (hyperthyroidism) due to the action of antibodies stimulating the TSH receptor (R) named TSHR-Ab." (PMID 36902117, 2023). "Intense stimulation of TSHR by anti-TSHR antibodies (TRAb) leads to increased secretion of thyroid hormones, thyroxine (T4) and triiodothyronine (T3), resulting in hyperthyroidism." (PMID 35370997, 2022). "In hyperthyroidism patients, TSHR autoantibodies (TRAb) stimulate the thyroid after binding to TSHR by increasing the production of intracellular cyclic AMP." (PMID 35942151, 2022). "immunized BALB/c female mice with an adenovirus expressing TSHR-289 once, and the rate of hyperthyroidism reached 100% at 6 week." (PMID 35813642, 2022). "Studies have proven that the proportion of hyperthyroidism induced by adenovirus carrying TSHR-289 was significantly higher than that of full-length wild-type adenovirus containing TSHR." (PMID 35813642, 2022). "This is not surprising, because reconstitution autoimmunity is more commonly represented by autoantibody‐mediated disorders, and Graves’ hyperthyroidism and GO are driven by TSHR‐Ab." (PMID 35604323, 2022). "For example, electroporation was used to enhance the expression of human TSHR in vivo and induce hyperthyroidism in mice." (PMID 35813642, 2022). "The mechanism of hyperthyroidism in GD is the production of autoantibodies to the Thyroid Stimulating Hormone Receptor (TSH-R) that mimic the effects of the thyrotropin." (PMID 35877662, 2022).
hyperthyroidism (continued). "Thyroid-stimulating hormone receptor (TSHR) is a major thyroid self-antigen, and autoantibodies against TSHR are widely believed to be the cause of hyperthyroidism." (PMID 35245125, 2022). "Whilst providing a “healthful aging” in 1-year-old mice, it is possible that probiotics worsen hyperthyroidism following TSHR immunization." (PMID 33593429, 2021). "Abnormalities in immune system function lead to uncontrolled production of thyroid-stimulating hormone receptor (TSHR) autoantibodies (TRAb), thus inducing excessive thyroid hormone synthesis and consequently resulting in hyperthyroidism." (PMID 33530368, 2021). "Anti-TSHR antibodies, cyclic peptides and small molecule ligands are being developed as antagonists of TSHR activation with the potential to treat Graves’ hyperthyroidism and GO using the same drug." (PMID 32911689, 2020). "Such strategies preclude the requirement of inducing systemic hyperthyroidism or the use of TSHR agonists to enhance the therapeutic index for drug delivery, such as radio-iodine uptake." (PMID 32698392, 2020). "Graves’ hyperthyroidism is characterized by the presence of autoantibodies that stimulate the thyroid-stimulating hormone receptor (TSHR), resulting in uncontrolled secretion of excessive thyroid hormone." (PMID 32845332, 2020). "This approach resulted in a high incidence of induced hyperthyroidism accompanied by a sustained antibody response to TSHR." (PMID 32399893, 2020). "In this review, we first contrast what is known about TSHR autoantibodies in GD hyperthyroidism and GO to what has been found regarding IGF1R autoantibodies." (PMID 32911689, 2020). "These were administered to HLA-DR3 transgenic mice that had been primed for hyperthyroidism by TSHR cDNA immunization, and the TSHR peptide-pretreated mice showed a profound reduction in induced TRAbs and lower thyroid hormone levels." (PMID 32845332, 2020). "Alternatively, activation of TSHR-mediated proliferative cues in malignant thyrocytes can be minimized therapeutically by inducing pharmacologic hyperthyroidism, leading to suppression of endogenous TSH." (PMID 32698392, 2020). "TRAb is an antibody which is specific to TSHR, and it is believed to be the autoantibody most important for the development of hyperthyroidism." (PMID 31565653, 2019). "In case of GD, persistent increased levels of autoantibodies directed against TSHR stimulate the growth and function of thyroid follicular cells, thus, leading to development of goiter and hyperthyroidism." (PMID 29449887, 2018). "Stimulatory antibodies against the thyroid-stimulating hormone receptor (TSH-R) activate the thyroid gland which leads to hyperthyroidism." (PMID 30228914, 2018). "TRAb mimics the action of thyroid stimulating hormone (TSH) and stimulates the thyroid hormone receptor (TSHR), which results in hyperthyroidism (overactive thyroid gland) and goiter." (PMID 29310665, 2018). "In GD, anti-TSHR autoantibodies can bind to TSHR and stimulate the production and secretion of thyroid hormones, resulting in hyperthyroidism." (PMID 29992164, 2018). "GD is clinically characterized by hyperthyroidism, diffuse goiter and the presence of thyrotropin receptor (TSHR) antibodies." (PMID 28521825, 2017). "It is characterized by hyperthyroidism and specific thyroid autoantibodies against thyroid-stimulating hormone receptor (TSHR) and is also commonly accompanied by autoantibodies against thyroglobulin (TG) and thyroid peroxidase (TPO)." (PMID 29259988, 2017). "TSHR-autoantibodies bind to TSHR, mimicking the action of its ligand (TSH) and causing hyperthyroidism." (PMID 29190882, 2017). "The antibody-mediated autoimmune condition targeting the TSH receptor (TSHR) in the thyroid gland which results in hyperthyroidism can be replicated in mouse models, preferably in TSHR-immunised mice." (PMID 27368808, 2017). "Stimulatory TSHR auto-antibodies are directly responsible for the syndrome of hyperthyroidism in the development of GD." (PMID 28521825, 2017).
hyperthyroidism (continued). "Second, hyperthyroidism was attenuated in adult mice by injecting TSHR A-subunit protein before A-subunit adenovirus immunization." (PMID 28620373, 2017). "Remarkably, TSAb and hyperthyroidism were induced in approximately 20% of female BALA/c mice presumably through hijacking of the TSHR to the MHC class II presentation pathway." (PMID 27895620, 2016). "The thyroid-stimulating hormone receptor is not only a major regulator of thyroid function but also plays a major role in several thyroid pathologies, including hyperthyroidism, hypothyroidism, and thyroid tumors." (PMID 26858688, 2016). "In the original report, intramuscular adenovirus (ad)-TSHR immunization induced TSAb and hyperthyroidism symptoms in 55 and 33% of female and male BALB/c mice, respectively." (PMID 27895620, 2016). "Meanwhile, CBA/J, DBA/1J, and SJL/J mice were completely resistant to ad-TSHR-induced hyperthyroidism." (PMID 27895620, 2016). "The present study evaluated the role of TSHR signaling on bone metabolism in untreated hyperthyroidism patients." (PMID 26650844, 2015). "The availability of small molecule ligands for TSHR would widen the therapeutic interventions for thyroid cancer and patients with hyperthyroidism." (PMID 26441832, 2015). "Although the impacts of TSHR signaling on bone metabolism are not comparable to that of thyroid hormone, it is still valuable to define the independent role of TSHR signaling on bone metabolism especially in hyperthyroidism." (PMID 26650844, 2015). "In contrast, GD patients exhibit hyperthyroidism, which is due to excessive secretion of the thyroid hormone induced by specific autoantibodies to the thyrotropin receptor (TSHR) produced by TSHR-reactive B cells." (PMID 25127106, 2014). "Thyroid antibodies can serve as useful clinical predictors of thyroid dysfunction, for example, TPO-Ab and post partum thyroiditis and TSHR-Abs and neonatal hyperthyroidism." (PMID 23691429, 2013). "Transplacental passage of TSHR-Abs has been titrated to the development of neonatal hyperthyroidism to such a careful extent that the maternal level can be used as a predictor of neonatal dysfunction." (PMID 23691429, 2013). "GD is characterized clinically by hyperthyroidism, diffuse goiter and the presence of thyrotropin receptor (TSHR) antibodies." (PMID 22662162, 2012). "We have now investigated TSHR antibody production and hyperthyroidism induced by TSHR A-subunit adenovirus immunization of a larger family of strains (26 of the AXB and BXA strains)." (PMID 21738647, 2011). "Theoretically, the TSHR gene is a suitable candidate for genetic susceptibility to GD because it is a thyroid-specific gene, and it is well known that antibodies against the TSHR play a major role in activation of thyroid cells and hyperthyroidism." (PMID 22654556, 2011). "Studies in two small families of recombinant inbred strains showed that susceptibility to developing TSHR antibodies (measured by TSH binding inhibition, TBI) was linked to the MHC region whereas genes on different chromosomes contributed to hyperthyroidism." (PMID 21738647, 2011). "Mice of the B6 strain are “good antibody responders” to immunization with adenovirus expressing the TSHR or its A-subunit but rarely develop hyperthyroidism." (PMID 21738647, 2011). "Auto-antibodies against the thyroid-stimulating hormone receptor were shown to be responsible for the hyperthyroidism in GD." (PMID 20885778, 2010). "Congenital hyperthyroidism is a rare disease and most cases are caused by transplacental passage of maternal thyrotropin receptor (TSHR) antibodies, which leads to transient hyperthyroidism in infants of mothers with Graves' disease." (PMID 21274318, 2010). "These induce the production of stimulating anti-TSHR antibodies by B cells and anti-apoptotic mechanisms that lead to clinical hyperthyroidism." (PMID 15762980, 2005).
hyperthyroidism (continued). "The autoimmune process responsible for the hyperthyroidism and activation of orbital fibroblast (OFs) is the production of autoantibodies against the thyroid stimulating hormone receptor (TSHR), which increases the proliferation, hyaluronan (HA) production, and adipogenic differentiation of OFs." (PMID 40558705, 2025). "HM may also present with early-onset preeclampsia (prior to 20 weeks), signs of hyperthyroidism from hCG-mediated thyroid-stimulating hormone receptor activation, or ARDS from trophoblastic embolization." (PMID 40870919, 2025). "Meanwhile, some specialists consider this course of hyperthyroidism as a variant of GD caused by non-immunological and non-genetic mechanisms because elevated TSHR-Ab levels are found subsequently in these patients." (PMID 38813368, 2024). "In the present study, however, variants predicted to alter the structure of TSHR were found in only a minority of HT cats and were also seen in ET cats, suggesting that they are not sufficient on their own to cause hyperthyroidism." (PMID 39567583, 2024). "The thyroid stimulating hormone receptor (TSHR) is the main target antigen of the immune system in GD, which induces the synthesis of autoantibodies against it, stimulating the secretion of thyroid hormones and leading to gland hyperplasia and hyperthyroidism." (PMID 38878190, 2024). "Moreover, the success rate of genetic immunization with plasmids has been enhanced through the implementation of a specialized electroporation technique, which leads to a sustained antibody response to TSHR, leading to a high incidence of hyperthyroidism." (PMID 39280007, 2024). "No other significant associations between the TSHR locus and the FinnGen disease endpoints unrelated to hypo- or hyperthyroidism were observed." (PMID 38194289, 2024). "The present report describes for the first time a case of diffuse hyperthyroidism in a 30-year-old female patient who had normal levels of thyroid-stimulating hormone receptor antibodies (TSHR-Ab), slightly elevated plasma levels of thyroid hormones, and slightly increased thyroid blood flow." (PMID 38813368, 2024). "Interestingly, among the 2 family members with TSHR I640V, hyperthyroidism was activated in the early phase of pregnancy; thus, antithyroid medication was initiated." (PMID 38194289, 2024). "GD is an autoimmune disease of the thyroid which is caused by autoantibodies against the thyroid stimulating hormone receptor (TSHR) (TSHR Ab = TRAb), leading to an overproduction of thyroid hormones, overstimulation of the thyroid gland and consecutive hyperthyroidism." (PMID 37810891, 2023). "Hyperthyroidism is caused by the growth and reproduction of thyroid cells and persistent and uncontrolled thyroid stimulation resulting from the interaction of TRAB with TSHR in genetically predisposed individuals with GD." (PMID 35651979, 2022). "Most cases of neonatal hyperthyroidism are transient but may excessively harm multiple organ functions through the actions of maternal thyroid-stimulating hormone receptor antibodies on the neonatal thyroid gland." (PMID 35413827, 2022). "However, only 20% of the female NMRI mice immunized with TSHR cDNA developed hyperthyroidism and thyroid stimulating hormone receptor-stimulating antibody (TSAb), and none of the male NMRI mice developed hyperthyroidism in their experiment." (PMID 35813642, 2022). "The incidence and severity of hyperthyroidism were higher in STAT4-deficient mice than in wild-type and STAT6-deficient mice after immunization with adenovirus containing amino acid residues 1–289 of TSHR." (PMID 35813642, 2022). "Hyperthyroidism of GD is due to the liganding of thyrotropin receptor (TSHR) on thyroid cells by stimulatory autoantibodies, which act as a TSHR agonist and induce excessive secretion of thyroid hormones, causing the thyroid to escape the control of the pituitary gland." (PMID 35140607, 2021).
hyperthyroidism (continued). "Theoretically, the stimulation of the TSHR on metastatic lesions may lead to increased proliferation rate, tumor growth, and hormone release, as well as hyperthyroidism." (PMID 33926024, 2021). "TRAb binds to TSH receptor (TSHR) to activate thyroid gland, leading to hyperthyroidism and goiter." (PMID 33653401, 2021). "Graves’ hyperthyroidism was initially thought to be caused by excessive secretion of thyroid-stimulating hormone (TSH) by the pituitary gland, but the discovery of autoantibodies against TSH receptor (TSHR) in 1956 has established GD as an autoimmune disease." (PMID 33981318, 2021). "The TSHR is also found in orbital fibroblasts and the upper dermis where binding of TRAbs results in a proliferative response that contributes to the extrathyroidal signs seen in Graves’ hyperthyroidism, GO, and pretibial myxedema." (PMID 32845332, 2020). "In addition, Graves’ hyperthyroidism, in contrast to many other autoimmune conditions, has a specific autoantigen which is the extracellular domain of the TSHR." (PMID 32845332, 2020). "Nonimmune hyperthyroidism is caused by germline mutation of TSHR, resulting in constitutive activation of the intracellular signaling cascade." (PMID 29849619, 2018). "Taken together, in this study, we have successfully established a GD murine model with the pathological phenotype of GO simultaneously, indicating that the approach of genetic immunization of TSHR A subunit plasmid is an effective approach for induction of hyperthyroidism and orbitopathy." (PMID 28319174, 2017). "Finally, although TSHR autoantibodies are unusual, Graves’ hyperthyroidism is a common condition, with a prevalence of ~1%." (PMID 28620373, 2017). "We describe severe thyrotoxicosis in young members of a family with nonautoimmune hyperthyroidism caused by a C672W germline mutation in exon 10 of TSHR gene." (PMID 29225840, 2017). "These peptides were tested for their potency to induce tolerance in TSHR-immunised diseased mice after repeated intravenous administration of target doses—to mitigate disease manifestations such as thyroid enlargement, hyperthyroidism and retro-orbital fibrosis." (PMID 27368808, 2017). "Similarly, antibodies specific for TSHR were found mainly in patients with hyperthyroidism (9 of a total of 13 positives)." (PMID 28533776, 2017). "Stimulatory TSHR autoantibodies are directly responsible for hyperthyroidism in GD." (PMID 27486433, 2016). "Moreover, intradermal injection of TSHR DNA induced TSAb and hyperthyroidism in inbred female BALB/c mice at an incidence of 27%." (PMID 27895620, 2016). "Considering that the large portions of these patients still have TSH stimulating antibodies after reaching the remission status, the activated TSHR signaling might play a role in hyperthyroidism-related bone disease." (PMID 26650844, 2015). "In hyperthyroidism status, mice lacking TSHR showed profound bone loss with increased bone resorption compared to wild type mice, suggesting that TSH had protective effects in hyperthyroid-associated osteoporosis." (PMID 26650844, 2015). "Germline nonautoimmune hyperthyroidism due to an activating mutation in the thyroid stimulating hormone receptor gene is an uncommon disease." (PMID 25873976, 2014). "We identified a new TSHR germline mutation (I486N) in a neonate with non-autoimmune sporadic hyperthyroidism." (PMID 21835055, 2011). "Orbital involvement is not merely a byproduct of hyperthyroidism; rather, the same underlying immune processes involving TSHR antibodies are active in the orbits." (PMID 22654556, 2011). "However, in GD the main autoantigen is TSHR and antibodies against TSHR (TRAb) are found almost exclusively in patients with Graves’ hyperthyroidism." (PMID 22654555, 2011). "Finally, the EAGD model, in which TSHR cDNA is administered in an adenoviral vector, produces TSHR stimulating antibodies and hyperthyroidism." (PMID 21559421, 2011).